MDK (midkine)
Diseases named in the same sentence as MDK in open-access papers (continued):
Sharing a sentence is not in itself a finding about the gene and the disease.
glioblastoma (21 papers, 2016 to 2025). The most malignant astrocytic tumor (WHO grade IV). "Preclinical studies have demonstrated the efficacy of MDK and NCL inhibitors in cancers such as glioblastoma and pancreatic cancer, where MDK signaling is implicated in tumor progression and immune suppression." (PMID 40396179, 2025). "In cancer biology, midkine has been implicated in tumor progression in glioblastoma and neuroblastoma through ALK/NF-κB and Notch2/Hes1 signaling pathways." (PMID 41339619, 2025). "Midkine (MDK), a multifunctional growth factor, has been implicated in promoting tumor progression, yet its role in glioblastoma (GBM) remains insufficiently characterized." (PMID 40835683, 2025). "This includes VGF, which is linked to promoting growth and survival in glioblastoma and MDK, which is highly expressed in malignant tumours and has been shown to play a role in chemoresistance." (PMID 39540879, 2024). "The current focus of our research is whether glioblastomas with EGFRvIII mutation could directly participate in the regulation of MDK expression through the ERK/c-Fos signaling pathway." (PMID 40527884, 2025). "In glioblastomas, MDK is highly expressed and associated with poor prognosis." (PMID 40468625, 2025). "Our previous bioinformatics-based study found that midkine (MDK) was associated with poor prognosis of glioblastoma (GBM)." (PMID 34556138, 2021). "In glioblastoma, MDK was demonstrated to enhance EMT, migration, and invasion, presumably through the PI3K/AKT pathway." (PMID 40429950, 2025). "In summary, our study’s combination of computational and functional analyses provides novel insight into MDK as a key contributor to a distinct, aggressive glioblastoma phenotype." (PMID 40835683, 2025). "As shown for pancreatic carcinomas, Ad-MDK gene therapy enables glioblastoma-specific expression of oncolytic viruses, highlighting the use of MDK for the treatment of malignant glioblastomas." (PMID 38098484, 2023). "Because MDK has been implicated to promote the growth of neural stem cells and progenitor cells in vitro, it is likely that MDK is also involved in glioblastoma initiation." (PMID 38098484, 2023). "In fact, MDK has been shown to protect glioblastoma and neuroblastoma cells against cannabinoid and doxorubicin treatments, respectively." (PMID 35625997, 2022). "These previous reports are consistent with the growth-promoting effects of MDK on E&F-independent IDH1-wt glioblastomas with high mesenchymal activity." (PMID 32120790, 2020). "Similarly, inhibiting the MDK-NCL interaction has been proposed as a therapeutic strategy in glioblastoma and endometrial carcinoma." (PMID 39955556, 2025). "Despite these findings, the precise molecular mechanism by which MDK promotes glioblastoma progression and resistance remains unclear." (PMID 40468625, 2025). "Furthermore, although MDK has been extensively studied in glioblastomas, its interaction with key oncogenic factors and its role in regulating critical signalling pathways, such as Wnt/β‐catenin, require further investigation." (PMID 40468625, 2025). "Similarly, increased MDK levels in the CNS correlate with a poor prognosis and lower survival of glioblastoma patients, indicating an involvement of the growth factor in disease progression." (PMID 38098484, 2023). "Targeting the growth factor midkine (MDK) may offer improved treatment for glioblastoma, the most lethal brain cancer." (PMID 31811117, 2019). "By screening the small‐molecule inhibitor ACT001, the interaction between MDK and c‐Myc was successfully disrupted, thereby promoting apoptosis in TMZ‐resistant glioblastoma cells and inhibiting cell proliferation." (PMID 40468625, 2025). "Moreover, a phase Ib clinical trial has evaluated the combination of the ALK inhibitor crizotinib with standard therapy in newly diagnosed glioblastoma patients, suggesting that targeting the MDK‐ALK axis may offer a new therapeutic strategy to overcome drug resistance." (PMID 40468625, 2025).
glioblastoma (continued). "This investigation marks the initial discovery that the downregulation of the MDK gene effectively diminishes the proliferation, migration, and epithelial–mesenchymal transition (EMT) of glioblastoma multiforme (GBM) cells in response to hypoxic conditions." (PMID 38255198, 2024). "We further verified whether MDK has a chemotactic effect on macrophages by treating human THP-1 cell line with recombinant MDK protein and co-culturing them with different glioblastoma cell lines." (PMID 40527884, 2025). "With the substantial potential of primary glioblastoma cells for MDK secretion, we decided to assess whether local expression correlates to a systemic rise of MDK levels, which could potentially be used for the non-invasive identification of MDKhigh tumors." (PMID 40835683, 2025). "Therapies with siRNA, oligoDNA, and other drugs inhibiting MDK have not yet been tested for CNS-related neoplastic diseases but might represent enormous therapeutic potential for the treatment of glioblastomas." (PMID 38098484, 2023).
breast carcinoma (20 papers, 2010 to 2025). "Although MDK levels have been identified as an independent marker of prognosis in breast cancer, being associated with metastasis and reduced disease-free survival, its utility as a diagnostic biomarker remains limited." (PMID 40429950, 2025). "Regulation of the tumor microenvironment also appears to be linked to MDK’s role in the progression of breast cancer." (PMID 40429950, 2025). "Overexpression of MDK rescued the loss of angiogenesis ability mediated by knockdown of USP12 in breast cancer cells in vitro and in vivo." (PMID 34759262, 2021). "Notably, this study also found that high MDK expression in the breast tissue of young women correlated with a higher Gail-5 score, a model for predicting breast cancer risk." (PMID 40429950, 2025). "We also found that Ugonin P significantly suppresses MDK synthesis in both lung and breast cancer cells." (PMID 40520001, 2025). "In conclusion, Ugonin P effectively inhibits lung and breast cancer-promoted osteoclast formation by reducing MDK production through upregulation of miR-223-3p expression." (PMID 40520001, 2025). "The deubiquitinase ubiquitin-specific protease 12 (USP12) can promote angiogenesis in breast cancers by stabilizing MDK and promoting the downstream activation of the AKT pathway and VEGF receptor 3 (VEGFR3)." (PMID 40429950, 2025). "NF-κB is also involved in MDK signaling in breast cancer, with MDK activating NF-κB and downstream NR3C1 to promote proliferation and migration of tumor cells by facilitating EMT." (PMID 40429950, 2025). "In breast cancer, MDK knockdown inhibited cell growth and invasion by regulating the NF-κB-NR3C1 pathway." (PMID 40520001, 2025). "MDK overexpression is observed across all major breast cancer subtypes, including estrogen receptor (ER)-positive, human epidermal growth factor receptor 2 (HER2)-positive, and triple-negative breast cancer (TNBC)." (PMID 40429950, 2025). "In a comparative study, serum MDK was found to not only be elevated in breast cancer patients, but to decrease following the surgical removal of the tumor." (PMID 40429950, 2025). "In previous studies, we found that hypoxia increased the expression of MDK in human umbilical vein endothelial cells and MDK promoted the proliferation and migration of human breast cancer cells." (PMID 38255198, 2024). "Mechanistically, we identified that MDK was determined to be direct downstream protein of miR-1275 which initiated PI3K/Akt signaling in breast cancer cells." (PMID 36594100, 2023). "Plasma MDK in patients with breast cancer was found to be elevated compared to normal controls (ductal carcinoma in-situ, DCIS: p < 0.05; primary invasive cancer without distant metastasis: p < 0.001; metastatic disease: p < 0.00)." (PMID 37240085, 2023). "The expression of Midkine is abnormally upregulated in various human cancers, especially in liver, lung and breast cancer." (PMID 37047258, 2023). "By analyzing the breast cancer data with 3,798 spots and 36,601 genes, we found clear spatial signaling directionality of midkine signaling, which was identified to be the most active, and the regions receiving such signals." (PMID 36690742, 2023). "Our data revealed that USP12 and MDK were both highly expressed in breast cancer tissues compared with adjacent tissues." (PMID 34759262, 2021). "Collectively, our study revealed that USP12 is responsible for deubiquitinating and stabilizing MDK, which induces breast cancer metastasis by promoting angiogenesis, and provides a novel regulatory mechanism for breast cancer metastasis." (PMID 34759262, 2021). "There was a strong positive relationship between USP12 and MDK protein expression in clinical breast cancer samples." (PMID 34759262, 2021). "We further verify that USP12 induces breast cancer angiogenesis through MDK by using the mouse aortic ring assay." (PMID 34759262, 2021).
breast carcinoma (continued). "To further validate the clinical significance of USP12 and MDK in breast cancer metastasis, we detected their expression levels in breast cancer clinical tissue specimens." (PMID 34759262, 2021). "Consistent with USP12, high MDK expression also predicted a poor prognosis in breast cancer patients." (PMID 34759262, 2021). "One study found breast cancer patients to have higher plasma levels of midkine than their healthy controls." (PMID 29486735, 2018). "MDK is elevated in the plasma of patients with breast cancer, relative to normal plasma." (PMID 40429950, 2025). "In this study, we confirmed that cancer cells promote bone metastasis through increasing osteoclast formation, which can be inhibited by Ugonin P. We also determined that MDK is highly expressed in lung and breast cancer patients and is related with osteoclast differentiation." (PMID 40520001, 2025). "Furthermore, MDK has been evaluated as a component in gene panels for predicting breast cancer prognosis." (PMID 40429950, 2025). "Among the elevated MDK forms, both conventional and tMDK have been detected in breast cancer samples, although the functional significance of tMDK remains unclear." (PMID 40429950, 2025). "In breast cancer, MDK treatment led to a reduction in natural killer (NK) cells." (PMID 40429950, 2025). "In breast cancer with leptomeningeal metastases, circulating tumor cells in the cerebrospinal fluid (CSF) were found to have elevated MDK, which could interact with circulating macrophages and monocytes via the LRP1 or SORL1 receptors." (PMID 40429950, 2025). "MDK has been identified as a potential biomarker in breast cancer." (PMID 40429950, 2025). "Thus, MDK represents an appealing drug target to interfere with various pro-tumor processes in breast cancer." (PMID 40429950, 2025). "In breast cancer, MDK was identified as a direct downstream protein of miR-1275." (PMID 39014225, 2024). "Low miR-1275 induced chemoresistance of breast cancer cells via MDK mediated PI3K/Akt Axis." (PMID 37240085, 2023). "In human cancers, compared to other well-known growth factors, MDK expression is most significantly upregulated in cancers, especially in liver, kidney and breast cancers, correlating with clinical outcomes and inversely correlating with phosphorylated AMPK levels." (PMID 35487917, 2022). "Indeed, a recent study reported that USP12 deubiquitinates and stabilizes MDK and this stabilization promotes breast cancer angiogenesis." (PMID 35487917, 2022). "Moreover, the USP12 level was positively correlated with the MDK level in breast cancer tissue samples." (PMID 34759262, 2021). "Collectively, these results indicate that USP12 could promote angiogenesis in breast cancer through upregulating MDK." (PMID 34759262, 2021). "To assess whether USP12 promotes breast cancer angiogenesis by upregulating MDK, we overexpressed MDK in MDA-MB-231 and MCF7 cells with USP12 knockdown and measured angiogenesis by HUVEC migration and tube formation assays in vitro." (PMID 34759262, 2021). "MDK gene was knocked down at the same time in breast cancer cells overexpressing USP12." (PMID 34759262, 2021). "Moreover, coordinated upregulation of USP12 and MDK was demonstrated in clinical breast cancer samples." (PMID 34759262, 2021). "Furthermore, our data revealed that USP12 promoted breast cancer metastasis by upregulating MDK protein levels." (PMID 34759262, 2021). "In a study conducted on breast cancer and MDK levels, it was concluded that MDK levels may be more beneficial than currently used tumor markers in the diagnosing and discriminating of primary and metastatic breast cancer." (PMID 31905498, 2020). "Furthermore, angiogenic role of midkine has been shown by the observation that MK transfection into the breast carcinoma line, MCF-7, accelerated tumor growth, and increased tumor vascularity after implantation of the cells in nude mice." (PMID 24281085, 2010).
breast carcinoma (continued). "Also, high USP12 and MDK expression predicts poor prognosis in breast cancer patients." (PMID 37752518, 2023). "Increased MDK expression in non-small cell lung cancer (NSCLC) is related with malignant traits and influences breast cancer progression through the NF-κB-NR3C1 pathway, also protecting cancer cells from cannabinoid and doxorubicin treatments." (PMID 40520001, 2025). "In the HER2-negative breast cancer cohort treated with Bevacizumab, MMP2, COL5A2, COL6A1, DLK1, and MDK were identified as predictive of treatment response, aligning with their documented roles in angiogenesis and stromal interactions." (PMID 41139924, 2025). "The reduction of miR‐1275 increases the ratio of cancer stem cells by targeting MDK/AKT axis, thus promoting the chemotherapy resistance of breast cancer cells." (PMID 38263865, 2024). "USP12 can also activate the Akt signaling pathway in tumors and endothelial cells by upregulating MDK, and promoting VEGFR3 expression through the mTOR signaling pathway, which then promotes the occurrence and progression of breast cancer." (PMID 37752518, 2023). "The results showed that MDK expression is negatively correlated with the AMPK signaling pathway in several different cancers, such as liver cancer, kidney cancer, and breast cancer." (PMID 35487917, 2022). "Consistent with the pattern for USP12, high MDK expression predicted lower DMFS and overall survival (OS) in breast cancer." (PMID 34759262, 2021). "In an orthotopic breast cancer model, silencing USP12—an MDK stabilizing protein—reduced lung metastases in a manner that could be reversed through MDK supplementation." (PMID 40429950, 2025). "Furthermore, ligand‐receptor analysis showed that COL1A1/COL1A2‐SDC4/CD44 and MDK/NCL presented the highest communication probability, suggesting that these ligand‐receptor pairs are necessary for LN metastasis in breast cancer." (PMID 40492378, 2025). "Interestingly in most cancers, including breast cancer, increased CD68+ macrophage infiltration is correlated with poorer outcomes, similar to the trend seen with MDK." (PMID 40429950, 2025).
ovarian carcinoma (19 papers, 2008 to 2025). A malignant neoplasm originating from the surface ovarian epithelium. "Bioinformatic analyses have identified MDK as one of the key genes implicated in the progression, metastasis, and drug resistance of ovarian cancer." (PMID 40500394, 2025). "Although MDK is generally linked to the augmentation of therapeutic resistance, in ovarian cancer, evidence has emerged that both corroborate and contradict this notion." (PMID 40429950, 2025). "MDK secreted from ovarian cancer epithelial cells can also regulate cancer-associated fibroblasts by binding to NCL/syndecan 2 (SDC2)/LRP1." (PMID 40429950, 2025). "Epithelial ovarian cancer (EOC) is among the most common cancers for women worldwide, and the association of MDK with ovarian cancer has been studied for a long time." (PMID 37240085, 2023). "Our study has primarily focused on the role of MDK-NCL in ovarian cancer cells, but further investigation into the role of MDK-NCL within the TME is warranted." (PMID 40036264, 2025). "MDK has been proposed to suppress apoptosis in ovarian cancer, as reducing MDK mRNA via miR-124 promoted apoptosis of SKOV3 cells." (PMID 40429950, 2025). "Another study found that serum MDK demonstrated a significant increase from healthy patients to late-stage ovarian cancer, with benign and early-stage tumors serving as intermediate points." (PMID 40429950, 2025). "Midkine was identified as a potential biomarker for differentiating ovarian cancer from benign tumors and population controls." (PMID 40429950, 2025). "Immunohistochemical analysis indicates that MDK was elevated in ovarian cancer, and serous ovarian cancer in particular." (PMID 40429950, 2025). "In contrast, another study demonstrated that MDK can suppress cisplatin resistance in certain ovarian cancer cell lines." (PMID 40500394, 2025). "To clone a new carrier cell with significant antitumor effect, we cloned cells from EHMK cells by limiting dilution and examined the antitumor activity of each cell clone infected with AdE3‐midkine in HEY ovarian cancer cells." (PMID 30548997, 2019). "The effect of DIG-MSK was also evident on the loading of Sp1 on the other gene promoters: XIAP whose down-regulation can induce cell death, CRABP1, a gene involved in the development of ovarian carcinoma, and MDK that is a marker in ovarian cancer." (PMID 25110883, 2014). "Available data are consistent with a putative role for both AGR2 and MDK in oncogenesis and tumor progression, including ovarian cancer." (PMID 20525245, 2010). "Furthermore, MDK expression is induced in association with oncogenesis, inflammation and wound healing and is over-expressed in various human cancers, including ovarian cancer and may contribute to the development of chemotherapy drug resistance." (PMID 20525245, 2010). "There is a paucity of data characterising the plasma concentrations of MDK in ovarian cancer patients." (PMID 20525245, 2010). "In addition to MDK itself, both the LRP1 and ALK receptors have been found to be associated with ovarian cancer." (PMID 40429950, 2025). "In distinguishing benign tumors from ovarian cancer, a marker panel that included MDK was found to have a significantly higher area under the curve (AUC) than either cancer antigen 125 (CA125) or human epididymis protein 4 (HE4), which are the standard biomarkers for ovarian cancer." (PMID 40429950, 2025). "MDK and its receptors have been demonstrated to be affiliated with ovarian cancer." (PMID 40429950, 2025). "Notably, MDK did have some weaknesses, as it was less helpful at discriminating early-stage ovarian cancer from benign disease and had poor sensitivity in the cancer vs. benign comparison groups." (PMID 40429950, 2025). "The apparent pair of MDK_LRP1 among the three groups suggested that inhibition of the MDK_LRP1 pair might be an effective therapeutic target for ovarian cancer to reduce myeloid inhibitory cell differentiation (MDSCs)." (PMID 35935940, 2022).